PLBD2 (phospholipase B domain containing 2)
Description:
Putative aminopeptidase.
Synonyms: p76; PLBL2
Tractability: Antibody: UniProt predicts a signal peptide or a membrane-spanning region; its Gene Ontology location is reachable by antibodies, with medium confidence. PROTAC: ubiquitination databases record sites on it; its protein half-life has been measured.
Gene: Protein-coding gene on chromosome 12 (113,358,544 to 113,391,629, forward strand). Ensembl gene ENSG00000151176.
Subcellular location: Lysosome lumen
Gene Ontology:
Molecular function: protein binding; phospholipase activity
Cellular component: extracellular exosome; lysosomal lumen; extracellular region; lysosome
Genetic constraint (gnomAD): Loss-of-function variants: 52 observed, 62.71 expected, observed/expected ratio (o/e) 0.83, 90% interval 0.66 to 1.04. The upper end of that interval is the gene's LOEUF score, 1.04, which puts it in group 4 of 6, group 1 being the genes least tolerant of losing a copy. Missense variants: 728 observed, 716.44 expected, observed/expected ratio (o/e) 1.02, 90% interval 0.95 to 1.08. Synonymous variants: 314 observed, 297.59 expected, observed/expected ratio (o/e) 1.06, 90% interval 0.96 to 1.16.
Homologues: Orthologues: chimpanzee PLBD2 (98% identical), macaque PLBD2 (96% identical), pig PLBD2 (83% identical), dog PLBD2 (83% identical), mouse Plbd2 (81% identical), guinea pig PLBD2 (80% identical), rat Plbd2 (80% identical), rabbit PLBD2 (72% identical), tropical clawed frog plbd2 (59% identical), zebrafish plbd2 (58% identical), Caenorhabditis elegans Y37D8A.2 (39% identical). Paralogues in human: PLBD1 (31% identical).
Diseases named in the same sentence as PLBD2 in open-access papers:
PLBD2 is named in the same sentence as 6 diseases in open-access papers, as found by Europe PMC text mining. Sharing a sentence is not in itself a finding about the gene and the disease. The quoted sentences say what the papers report.
Batten’s Disease (1 paper, 2025). "Other proteins enriched in UBQLN24XALS IPs included BTBD2, which encodes a Ub E3 ligase involved in cytoskeletal dynamics and Top1-mediated chromatin relaxation, and phospholipase B D2 (PLBD2), a lysosomal phospholipase that has been implicated in the lysosomal storage disorder, Batten’s Disease." (PMID 41561437, 2025).
cancer (2 papers, 2022 to 2023). A tumor composed of atypical neoplastic, often pleomorphic cells that invade other tissues. "Next, using the IPA database combined with literature mining, we found that of the 150 hypoxia-increased proteins, Putative phospholipase B-like 2 (PLBD2) have not been previously associated with cancer." (PMID 37349288, 2023). "Studies are needed to elucidate the role of PLBD2 in cancer." (PMID 37349288, 2023).
PLBD2 also shares sentences with these, for which no sentence is quoted: hypothyroidism (1 paper); lung carcinoma (1); lysosomal storage disorder (1); skin aging (1).